ADAD1 (adenosine deaminase domain containing 1)
Description:
Required for male fertility and normal male germ cell differentiation (By similarity). Plays a role in spermatogenesis (By similarity). Binds to RNA but not to DNA (By similarity).
Synonyms: TENR
Tractability: No criterion of Open Targets' tractability assessment is met for any kind of drug.
Gene: Protein-coding gene on chromosome 4 (122,378,966 to 122,429,802, forward strand). Ensembl gene ENSG00000164113.
Subcellular location: Nucleus
Gene Ontology:
Molecular function: double-stranded RNA adenosine deaminase activity; double-stranded RNA binding; adenosine deaminase activity; RNA binding
Biological process: adenosine to inosine editing; RNA processing
Cellular component: cytoplasm; nucleolus; nucleus
Genetic constraint (gnomAD): Loss-of-function variants: 32 observed, 55.24 expected, observed/expected ratio (o/e) 0.58, 90% interval 0.44 to 0.78. The upper end of that interval is the gene's LOEUF score, 0.78, which puts it in group 3 of 6, group 1 being the genes least tolerant of losing a copy. Missense variants: 527 observed, 618.63 expected, observed/expected ratio (o/e) 0.85, 90% interval 0.79 to 0.92. Synonymous variants: 220 observed, 210.44 expected, observed/expected ratio (o/e) 1.05, 90% interval 0.94 to 1.17.
Homologues: Orthologues: macaque ADAD1 (98% identical), chimpanzee ADAD1 (98% identical), dog ADAD1 (92% identical), rabbit ADAD1 (91% identical), pig ADAD1 (91% identical), mouse Adad1 (89% identical), rat Adad1 (88% identical), guinea pig ADAD1 (80% identical), tropical clawed frog adad1 (61% identical), zebrafish adad1 (47% identical), Drosophila melanogaster Zn72D (10% identical), Drosophila melanogaster blanks (7% identical), and 3 more. Paralogues in human: ADAD2 (28% identical), ADARB1 (25% identical), ADARB2 (24% identical), ADAR (24% identical), ADAT1 (17% identical), ILF3 (13% identical), STAU1 (12% identical), STRBP (12% identical), STAU2 (12% identical), ZFR (11% identical), ZFR2 (11% identical), ILF2 (10% identical), and 2 more.
Diseases named in the same sentence as ADAD1 in open-access papers:
ADAD1 is named in the same sentence as 23 diseases in open-access papers, as found by Europe PMC text mining. Sharing a sentence is not in itself a finding about the gene and the disease. The quoted sentences say what the papers report.
colon cancer (3 papers, 2020 to 2024). "Our findings indicated that DEDD2, GTF2H5, SNRPA1, BICD1, CELF1, and CLK3 were prognostic risk factors for colon cancer, while ADAD1, CMTR1, HNRNPUL1, FTSJ3, WDR43, THUMPD3, SNRPF were prognostic protective factors." (PMID 36212157, 2022). "Among the protective prognostic factors, high levels of ADAD1 have been reported to be strongly associated with the prognosis of colon cancer patients, and its improvement of patient prognosis may be associated with CD4+ T cells." (PMID 36212157, 2022). "Additionally, ADAD1 and DLG3, related to CD4+ T cells, were significantly associated with the prognosis of patients with colon cancer." (PMID 32571262, 2020).
Azoospermia (2 papers, 2021 to 2023). Absence of any measurable level of sperm,whereby spermatozoa cannot be observed even after centrifugation of the semen pellet. "Reduced testicular or sperm ADAD1 expression was found in male patients and was particularly associated with non-obstructive azoospermia suggesting a role in spermatogenesis." (PMID 37552671, 2023).
infertile (2 papers, 2020 to 2023). "Our results are in harmony with previous studies on mice which reported that Adad1/Tenr deficient male mice are infertile due to abnormal sperm development." (PMID 37552671, 2023). "Depletion of NSUN7 or ADAD1 are known to cause infertility, suggesting that RMPs that are selectively expressed in meiotic stages of spermatogenesis are essential for proper sperm formation and/or maturation." (PMID 32375858, 2020).
teratospermia (2 papers, 2020 to 2022). "Mutation of either ADAD1 or ADAD2 resulted in males sterility with ADAD1 mutant mice displaying teratozoospermia." (PMID 35173218, 2022). "Mutation of either Adad resulted in complete male sterility with Adad1 mutants displaying severe teratospermia and Adad2 mutant germ cells unable to progress beyond round spermatid." (PMID 32665638, 2020).
autoimmune disease (1 paper, 2025). A disorder resulting from loss of function or tissue destruction of an organ or multiple organs, arising from humoral or cellular immune responses of the individual to their own tissue constituents. "Our genome-wide pleiotropy study further identified a gene cluster on the 4q27 chromosome region, encompassing KIAA1109, IL2, IL21, and ADAD1 genes, reporting a strong literature support for association with most autoimmune diseases and AD." (PMID 41009683, 2025).
breast cancer (1 paper, 2025). A primary or metastatic malignant neoplasm involving the breast. "This study hypothesized that epigenetic processes, including DNA methylation, influence the expression of identified CG or testis-specific genes, such as SYCP1, ADAD1, SYCE1, PRSS54, DMRTC2, and TEX101, in breast cancer (BC), normal breast (NB), and chronic myelogenous leukemia (CML) cell lines." (PMID 41411337, 2025).
cyst (1 paper, 2023). A sac-like closed membranous structure that may be empty or contain fluid or amorphous material. "Interestingly, we observed both nuclear and cytoplasmic localization of Adad1 in early spermatogonia (1 cell and cyst of up to 4 cells) and in oogonia/oocytes in nests or cysts (arrows), whereas later stage germ cells showed primarily cytoplasmic localization." (PMID 37552671, 2023).
leukemia (1 paper, 2025). A malignant (clonal) hematologic disorder, involving hematopoietic stem cells and characterized by the presence of primitive or atypical myeloid or lymphoid cells in the bone marrow and the blood. "Leukemia showed an inverse trend, with SYCP1 and ADAD1 hypermethylated, while PRSS54 was strikingly hypomethylated (~0.08 vs. ~ 0.86 normal)." (PMID 41411337, 2025). "ADAD1 hypermethylation in BC and PRSS54 hypomethylation in leukemia define cancer-specific epigenetic signatures." (PMID 41411337, 2025). "We comprehensively analyzed differential methylation, survival analysis (Kaplan-Meier), correlation (Spearman’s), and pathway enrichment analysis (GO/KEGG) of CG genes (SYCP1, ADAD1, SYCE1, PRSS54, DMRTC2, and TEX101) in BC and leukemia." (PMID 41411337, 2025). "In leukemia versus healthy donors, GO enrichment revealed that TEX101, ADAD1, PRSS54, and SYCE1 were the most enriched genes, whereas SYCP1 and DMRTC2 exhibited minimal enrichment." (PMID 41411337, 2025). "Functional enrichment identified ADAD1 and SYCP1 as key players in BC and leukemia pathways, respectively." (PMID 41411337, 2025). "In leukemia versus healthy blood donors, SYCP1, ADAD1, and SYCE1 were hypermethylated (~0.35 vs. ~ 0.17, ~ 0.84 vs. ~ 0.44, and ~0.45 vs. ~ 0.09, respectively), while PRSS54 was markedly hypomethylated (~0.08 vs. ~ 0.86)." (PMID 41411337, 2025). "Differential methylation analysis revealed cancer-specific patterns: ADAD1 was hypermethylated in both malignancies, while PRSS54 was hypomethylated in leukemia." (PMID 41411337, 2025).
hematological malignancies (1 paper, 2025). "ADAD1 showed a neutral correlation, while TEX101 displayed a slight positive trend, suggesting context-dependent regulation in hematological malignancies." (PMID 41411337, 2025).
tumor (1 paper, 2025). "In BC, ADAD1 exhibited pronounced hypermethylation, aligning with its role in meiotic silencing and potential tumor-suppressive effects when dysregulated." (PMID 41411337, 2025). "For tumor stage, SYCP1 and ADAD1 showed negligible positive correlations (ρ = 0.02, 0.08, respectively), while SYCE1, PRSS54 and DMRTC2 exhibited slight negative correlations." (PMID 41411337, 2025).
ADAD1 also shares sentences with these, for which no sentence is quoted: cancer (1 paper); celiac disease (1); inflammatory bowel disease (1); malakoplakia (1); male infertility (1); multiple sclerosis (1); Obesity (1); psoriasis (1); rheumatoid arthritis (1); sterility (1); systemic lupus erythematosus (1); type 1 diabetes (1); ulcerative colitis (1).